NGLY1 (N-glycanase 1)
Description:
Specifically deglycosylates the denatured form of N-linked glycoproteins in the cytoplasm and assists their proteasome-mediated degradation. Cleaves the beta-aspartyl-glucosamine (GlcNAc) of the glycan and the amide side chain of Asn, converting Asn to Asp. Prefers proteins containing high-mannose over those bearing complex type oligosaccharides. Can recognize misfolded proteins in the endoplasmic reticulum that are exported to the cytosol to be destroyed and deglycosylate them, while it has no activity toward native proteins. Deglycosylation is a prerequisite for subsequent proteasome-mediated degradation of some, but not all, misfolded glycoproteins.
Synonyms: PNGase; PNG1; FLJ11005; PNG-1; CDDG; CDG1V
Tractability: PROTAC: ubiquitination databases record sites on it; its protein half-life has been measured.
Target class: Enzyme; Hydrolase
Gene: Protein-coding gene on chromosome 3 (25,718,717 to 25,790,039, reverse strand). Ensembl gene ENSG00000151092.
Subcellular location: Cytoplasm
Pathways (Reactome):
Metabolism of proteins: N-glycan trimming in the ER and Calnexin/Calreticulin cycle
Gene Ontology:
Molecular function: peptide-N4-(N-acetyl-beta-glucosaminyl)asparagine amidase activity; protein binding
Biological process: glycoprotein catabolic process; positive regulation of BMP signaling pathway; protein folding
Cellular component: cytoplasm; cytosol; nucleus
Genetic constraint (gnomAD): Loss-of-function variants: 58 observed, 71.61 expected, observed/expected ratio (o/e) 0.81, 90% interval 0.65 to 1.01. The upper end of that interval is the gene's LOEUF score, 1.01, which puts it in group 4 of 6, group 1 being the genes least tolerant of losing a copy. Missense variants: 680 observed, 689.6 expected, observed/expected ratio (o/e) 0.99, 90% interval 0.93 to 1.05. Synonymous variants: 246 observed, 251.5 expected, observed/expected ratio (o/e) 0.98, 90% interval 0.88 to 1.09.
Gene-disease validity (ClinGen):
ClinGen rates the evidence that NGLY1 causes each of these diseases.
congenital disorder of deglycosylation 1 (autosomal recessive): Definitive.
Homologues: Orthologues: chimpanzee NGLY1 (99% identical), macaque NGLY1 (97% identical), dog NGLY1 (90% identical), pig NGLY1 (88% identical), mouse Ngly1 (85% identical), rabbit NGLY1 (81% identical), guinea pig NGLY1 (80% identical), rat Ngly1 (80% identical), tropical clawed frog ngly1 (63% identical), zebrafish ngly1 (56% identical), Drosophila melanogaster Pngl (32% identical), Caenorhabditis elegans png-1 (29% identical), and 11 more.
Diseases named in the same sentence as NGLY1 in open-access papers:
NGLY1 is named in the same sentence as 93 diseases in open-access papers, as found by Europe PMC text mining. Sharing a sentence is not in itself a finding about the gene and the disease. The quoted sentences say what the papers report.
developmental delay (19 papers, 2017 to 2025). "NGLY1 deficiency causes a rare congenital disorder characterized by developmental delay, seizures, and neurological and liver malfunction among many other symptoms." (PMID 38656405, 2024). "NGLY1 deficiency is an ultrarare genetic disorder that exhibits a complex clinical symptom that include seizures, hyperkinetic movement, alacrima, developmental delay, and abnormal liver function." (PMID 36875753, 2023). "NGLY1 deficiency is a ultrarare genetic disorder that is associated with an array of symptoms that include seizures, hyperkinetic movement, alacrima, developmental delay, and abnormal liver function." (PMID 36875753, 2023). "Patients with pathogenic mutations in NGLY1 have complex clinical symptoms including global developmental delay, motor disorder and liver dysfunction." (PMID 36875753, 2023). "This is a critical question as patients with NGLY1-deficiency display global developmental delay, movement disorder and growth retardation." (PMID 35294432, 2022). "Patients who are NGLY1-deficient display global developmental delay, movement disorder and growth retardation." (PMID 35294432, 2022). "In fact, a number of NGLY1 deficiency phenotypes, such as developmental delay, seizures, elevated liver enzymes, muscle weakness, scoliosis, and chronic constipation, are frequently observed in mitochondrial disorders." (PMID 35406718, 2022). "NGLY1 deficient patients show a broad spectrum of clinical features including developmental delay, hypolacrima or alacrima, seizure, intellectual disability, and motor deficits." (PMID 34120625, 2021). "N-glycanase 1 (NGLY1) deficiency is a rare inherited disorder characterized by developmental delay, hypolacrima or alacrima, seizure, intellectual disability, motor deficits, and other neurological symptoms." (PMID 34120625, 2021). "Similar to human patients, the rat model of NGLY1 deficiency, Ngly1−/−, shows developmental delay, movement disorder, somatosensory impairment, scoliosis, and learning disability." (PMID 34120625, 2021). "N-glycanase 1 (NGLY1) deficiency, an autosomal recessive disease caused by mutations in the NGLY1 gene, is characterized by developmental delay, hypolacrima or alacrima, seizure, intellectual disability, movement disorders and other neurological phenotypes." (PMID 32259258, 2020). "Here, we describe a Chinese infant with elevated liver transaminases, developmental delay, epilepsy (subclinical seizures) and light constipation who possesses two novel compound heterozygous mutations in NGLY1: a missense mutation and a termination mutation." (PMID 32576142, 2020). "Other notable, but perhaps less specific, features in the NKCC1-deficient child, including developmental delay and gastrointestinal problems, also overlap with those observed in NGLY1 deficiency." (PMID 33315011, 2020). "NGLY1 deficiency patients exhibit global developmental delay, seizures, involuntary movements, chronic constipation, osteopenia, small hands and feet, lack of tears and other symptoms." (PMID 32720893, 2020). "In this study, we generated the systemic Ngly1-deficient rodent model, Ngly1−/− rats, which showed developmental delay, movement disorder, somatosensory impairment and scoliosis." (PMID 32259258, 2020). "Patients with this rare disease, which is also known as NGLY1 deficiency, exhibit global developmental delay and other phenotypes including neuropathy, movement disorder, and constipation." (PMID 33315951, 2020). "Patients with NGLY1 deficiency have a variety of symptoms, including developmental delay, seizures, liver dysfunction, central and peripheral nervous system abnormalities, sweat gland abnormalities, and a lack of tears (alacrima)." (PMID 33315011, 2020). "Mutations in the human N-glycanase 1 (NGLY1) cause a rare, multisystem congenital disorder with global developmental delay." (PMID 28826503, 2017).
developmental delay (continued). "Recessive mutations in human NGLY1 result in a genetic disorder with various phenotypes including developmental delay, seizures, hypo-/alacrima, elevated liver enzymes, diminished deep tendon reflexes, muscle weakness, orthopedic manifestations, and chronic constipation." (PMID 33315951, 2020). "The present work revealed that Ngly1−/− rats represent the first systemic Ngly1-deficient model that develops symptoms that are characteristic of human NGLY1-deficient patients, including developmental delay, motor dysfunction, learning disability and other neurological phenotypes." (PMID 32259258, 2020). "Given that a number of NGLY1 deficiency phenotypes like developmental delay, neuropathy, muscle weakness, and seizures are also observed in mitochondrial disorders, they are considered to be one of the differential diagnoses in patients suspected of having NGLY1 deficiency." (PMID 33315951, 2020). "Importantly, children with mutations in the enzyme responsible for N-glycan removal (NGLY1) exhibit developmental delay, seizures, movement disorder, and other abnormalities." (PMID 33315951, 2020). "Recessive loss-of-function mutations in the evolutionarily conserved gene NGLY1 result in an ultra-rare genetic disease called NGLY1 Deficiency, which is characterized by global developmental delay, seizures, small head and extremities, chronic constipation, lack of tears, and floppy body." (PMID 29735526, 2018). "NGLY1-related congenital disorder of deglycosylation (NGLY1-CDDG) is a multisystemic neurodevelopmental disorder in which affected individuals show developmental delay, epilepsy, intellectual disability, abnormal liver function, and poor growth." (PMID 32576142, 2020). "Human patients with NGLY1 deficiency display an array of symptoms including global developmental delay, lack of tears, and chronic constipation." (PMID 37704604, 2023). "Recessive mutations in human NGLY1 lead to a disorder called NGLY1 deficiency (OMIM# 615273), which presents with multiple phenotypes, including but not limited to global developmental delay, movement disorder, seizures, microcephaly, liver disorders, and chronic constipation." (PMID 35406718, 2022). "Loss-of-function mutations in the NGLY1 gene cause NGLY1 deficiency, which is characterized by developmental delay, seizures, and a lack of sweat and tears." (PMID 33315011, 2020). "NGLY1-deficient patients show a host of phenotypes including global developmental delay, movement disorder, hypotonia, absent tears, peripheral neuropathy, constipation, and small feet and hands." (PMID 28826503, 2017). "In this dataset of the largest NGLY1 Deficiency cohort to date, the most commonly reported clinical features were global developmental delay/cognitive delay, absent speech, gait disturbance, hypotonia, alacrima, and severe constipation (all reported in > 86% of patients)." (PMID 36528660, 2022). "Thus, the diagnosis of NGLY1 deficiency was plausible for P1, even though she presented only with developmental delay and mild hypertransaminasemia, without the characteristic core features of NGLY1 deficiency, such as abnormal tear production, hyperkinetic movement disorder, or ataxia." (PMID 40643555, 2025). "In 2014, it was reported that NGLY1 deficiency could lead to NGLY1-congenital disorder of deglycosylation (CDDG), a disease characterized by developmental delay, intellectual disability, absence of or reduced tears and sweating, abnormal liver function, and motor dysfunction." (PMID 38067490, 2023).
Intellectual disability (10 papers, 2019 to 2024). "NGLY1 deficiency is characterized by a wide array of symptoms, such as global mental delay, intellectual disability, abnormal electroencephalography findings, seizure, movement disorder, hypolacrima or alacrima, and liver dysfunction." (PMID 39206713, 2024). "The phenotypes of this sample include moderate intellectual disability, delayed speech and language development, and echolalia, which was often observed in patients with NGLY1 deficiency." (PMID 35565658, 2022). "In addition, mutations in NGLY1, the gene encoding PNGase, are linked to motor impairment, intellectual disability, and neuropathy in humans." (PMID 30867060, 2019). "In 2012, bi-allelic compound mutations of NGLY1 were identified by whole-exome sequencing (WES) in a boy with congenital anomalies and/or intellectual disabilities." (PMID 35565658, 2022).
melanoma (8 papers, 2018 to 2025). A malignant, usually aggressive tumor composed of atypical, neoplastic melanocytes. "Knockdown of NGLY1 in melanoma cells caused ER-stress-associated apoptosis and sensitized the cancer cells to DNA alkylating agents, such as dacarbazine or temozolomide." (PMID 40643555, 2025). "Despite the discrepancy between CO and melanoma cells in response to NGLY1 loss, NGLY1-deficient CO cells, compared with the functional ones, showed higher susceptibility to either bortezomib, glutamate, hydrogen peroxide, or thapsigargin." (PMID 35322011, 2022). "Taken together, stress response-associated, GADD153-mediated apoptosis contributes to NGLY1 knockdown-induced melanoma cell death." (PMID 30385822, 2018). "Targeting NGLY1 induced pleiotropic responses, predominantly stress signalling-associated apoptosis and cytokine surges, which synergise with the anti-melanoma activity of chemotherapy and targeted therapy agents." (PMID 30385822, 2018). "We indeed observed that NGLY1 suppression leads to limited perturbation in human normal cells while causing detrimental outcomes in melanoma cells." (PMID 30385822, 2018). "Having observed ATF4 and GADD153 activation in NGLY1-suppressed melanoma cells, we tested whether the relevant signaling similarly alters in NGLY1-deficient COs." (PMID 35322011, 2022). "NGLY1 knockdown caused melanoma cell death and tumour growth retardation." (PMID 30385822, 2018). "Through global gene expression profiling, we discovered that, in addition to the activation of stress-response signalling, NGLY1 suppression in melanoma cells causes the significant upregulation of interferon genes that have well documented anticancer activity." (PMID 30385822, 2018). "NGLY1 is frequently overexpressed in cancers such as melanoma, and downregulation of NGLY1 has even been suggested as a potential cancer therapy." (PMID 40643555, 2025). "It has also been reported that the downregulation of NGLY1 results in melanoma cell death and a slowdown in tumor growth." (PMID 38067490, 2023). "The strong cytokine response induced by targeting NGLY1 in melanoma cells also contributed to the anti-melanoma effect triggered by NGLY1 inhibition." (PMID 35406718, 2022). "In a more recent study, Yu-Chieh Wang’s group reported that melanoma patient samples and cells lines express significantly higher levels of NGLY1 compared to primary melanocytes." (PMID 35406718, 2022). "Our results support a conclusion that human normal and melanoma cells present distinct features in response to NGLY1 suppression." (PMID 30385822, 2018). "Upon NGLY1 knockdown, melanoma cells showed morphological features of apoptosis, including shrinkage, fragmentation and detachment." (PMID 30385822, 2018). "In fact, the abundance of GRP78/94 proteins in melanoma cells determined by mass spectrometry appeared to drop in response to NGLY1 suppression." (PMID 30385822, 2018). "Many proteins also presented differential abundance in melanoma cells in response to NGLY1 knockdown." (PMID 30385822, 2018). "In contrast to human normal melanocytes, a majority of tested melanoma cell lines showed upregulation of NGLY1." (PMID 30385822, 2018). "The growth of melanoma tumours established with SK-MEL-2 cells in mice was impeded by the induced knockdown of NGLY1." (PMID 30385822, 2018). "We examined how NGLY1 expression affects viability, tumour growth, and responses to therapeutic agents in melanoma cells and an animal model." (PMID 30385822, 2018). "Pharmacological and molecular biology tools that inactivate NGLY1 elicited highly similar responses in melanoma cells." (PMID 30385822, 2018). "Having elevated contents of GlcNAc-asparagine-containing peptides and the differential abundance of specific proteins detected in NGLY1-knockdown melanoma cells, we examined proteomic changes in melanoma cells treated with our NGLY1 inhibitors." (PMID 30385822, 2018).
melanoma (continued). "The overexpression of exogenous human NGLY1 significantly attenuated the NGLY1 knockdown-mediated induction of IFNβ and IL-29 in melanoma cells." (PMID 30385822, 2018). "In this study, we revealed the significance and molecular mechanisms of NGLY1 as a novel target in melanoma for the induction of cancer cell-specific apoptosis and the development of new anticancer approaches." (PMID 30385822, 2018). "Due to the lack of optimised small molecules that specifically inactivate human NGLY1, we aimed to develop novel NGLY1 inhibitors and test their potential anti-melanoma use." (PMID 30385822, 2018). "In contrast to substantial perturbation induced by NGLY1 knockdown in melanoma transcriptomes, the disruption of NGLY1 expression in normal hPSCs and their differentiated derivatives caused limited changes in their gene expression networks." (PMID 30385822, 2018). "The enhanced phosphorylation of eIF2α was observed in melanoma cells due to the treatment of tunicamycin and NGLY1 knockdown, indicating the activation of the eIF2α signalling as the upstream of ATF4." (PMID 30385822, 2018). "Our data demonstrated that these cytokine surges play an important role in melanoma cell death as the consequence of NGLY1 inhibition." (PMID 30385822, 2018). "Our results reveal that, while highly upregulated in melanoma cells, NGLY1 appears to be dispensable for the vitality of human normal cells even in a highly sensitive state like the embryonic stage." (PMID 30385822, 2018). "Using transcriptomic analysis, we identified a group of genes (~750 gene probes corresponding to ~700 genes) that were significantly (P < 0.01) and commonly upregulated or downregulated between control and NGLY1-knockdown melanoma cells." (PMID 30385822, 2018). "Through proteomic analysis, we not only observed a higher content of peptides containing GlcNAc-asparagine residues but also identified proteins showing altered abundance in melanoma cells with NGLY1 inhibition." (PMID 30385822, 2018). "Notably, NGLY1 is highly expressed in certain human cancer cells, such as melanoma and ovarian cancer, while being low in their corresponding normal tissues like skin and ovary." (PMID 38067490, 2023). "Additionally, we will also investigate the potential therapeutic utility of NGLY1 inhibitors in the treatment of melanoma, multiple myeloma, and acute lymphocytic leukemia." (PMID 38067490, 2023). "Several other genes that are also involved in stress response signaling and significantly induced in NGLY1-knockdown melanoma cells were not upregulated in NGLY1-deficient COs." (PMID 35322011, 2022). "In this study, we systematically and mechanistically examined the significance of NGLY1 in melanoma cells and how it may be exploited as a novel anticancer target." (PMID 30385822, 2018). "We tested whether NGLY1 suppression enhances the anticancer activity of dacarbazine and temozolomide that are commonly used to treat melanoma." (PMID 30385822, 2018). "Compared with normal cells, NGLY1 was upregulated in melanoma cell lines and patient tumours." (PMID 30385822, 2018). "Similar alteration patterns associated with the differentially abundant proteins identified in the NGLY1-knockdown cells were observed in melanoma cells treated with NM-350, further supporting the NGLY1-inhibitory and anticancer activity of our novel compounds." (PMID 30385822, 2018). "Using a xenograft tumour model, we test the anti-melanoma response of NGLY1 suppression." (PMID 30385822, 2018). "In addition, the expression and activation of IRF3 and IRF7 proteins was enhanced in melanoma cells with NGLY1 knockdown." (PMID 30385822, 2018). "Our work demonstrated the significance of NGLY1 in melanoma cells, provided mechanistic insights into how NGLY1 inactivation leads to eradication of melanoma with limited impact on normal cells, and suggested that targeting NGLY1 represents a novel anti-melanoma strategy." (PMID 30385822, 2018).